HOXA9 (homeobox A9)
Diseases named in the same sentence as HOXA9 in open-access papers (continued):
Sharing a sentence is not in itself a finding about the gene and the disease.
leukemia (continued). "It is well established that HOXA9 and MEIS1 overexpression drives leukemogenesis in MLL-r leukemia." (PMID 34698191, 2021). "In MLL fusion-mediated leukemia, MLL fusion directly activates the expression of MYC and HOXA9." (PMID 34310280, 2021). "DOT1L is a therapeutic target for MLL-r leukemia: genome-wide hypermethylation of H3K79 is characteristic to the cancer 24 and DOT1L's catalytic activity is required for expression of MLL-target genes, such as HoxA9 and Meis1." (PMID 34373735, 2021). "Accordingly, HOXA9 and MYC synergistically induce leukemia in mouse models." (PMID 34310280, 2021). "Probe intensities of HOXA9 and MEIS1 are plotted separately by leukemia phenotype (ALL or AML) (B)." (PMID 34310280, 2021). "Combined expression of MYC and HOXA9 induced leukemia, whereas single gene transduction of either did not, indicating a synergy between MYC and HOXA9." (PMID 34310280, 2021). "Among the HOXA9 target genes, BCL2 and SOX4 synergistically induced leukemia with MYC." (PMID 34310280, 2021). "Indeed, co-expression of HOXA9, BCL2, or SOX4 promoted MYC-mediated leukemogenesis, while MYC alone was insufficient to induce leukemia in vivo." (PMID 34310280, 2021). "Given that HOXA9, the most important downstream gene in MLL leukemia, was reported to have enhancer-binding preference and to rewire leukemia-specific enhancers, we speculated that HOXA genes might mediate the programming of the SEELA enhancer." (PMID 33143730, 2020). "Although representation of a nontargeting control sgRNA did not change significantly in vivo, 5 of 5 sgRNAs targeting the positive control Hoxa9, essential for MLL-AF9 leukemia cells, showed a median depletion of more than 2-fold, demonstrating that the screen was robust." (PMID 32460032, 2020). "Importantly, in SEM cells constitutively expressing ectopic retroviral mouse Hoxa9 (SEMHOXA9), USF2 knock-down had little effect on cell growth, suggesting that HOXA9 is a functional and essential downstream gene of USF2 in USF2-mediated leukemia propagation." (PMID 33001025, 2020). "However, expression of specific genes, such as HOXA9 and MEIS1, is strongly dependent on DOT1L specially in leukemias induced by MLL-fusion proteins." (PMID 33104701, 2020). "For example, HOXA9 is extensively active in blocking differentiation of hematopoietic and lymphoid cancer, and participates in the characteristic myeloid differentiation block in MN1 (Meningioma 1) leukemia." (PMID 31013831, 2019). "They reported that combination of EPZ004777 and MI-2-2 (an inhibitor of MLL–Menin interaction) enhanced the down-regulation of important leukemia genes (i.e., MYC, HOXA9, and MEIS1) and anti-proliferative effects against MLL-r leukemia cells, compared to either single-agent treatment." (PMID 31157223, 2019). "In vivo, the presence of Hoxa9 expressed alone in murine bone marrow cells is not sufficient to rapidly induce leukemia (>6 months) whereas concomitant expression of Hoxa9 with Meis1 greatly shortened this period (approximately 67 days)." (PMID 31213012, 2019). "Furthermore, HOXA9 and MEIS1 have been reported as target genes of oncogenic MLL-AF9 fusion proteins in human leukemia." (PMID 30003105, 2018). "Mice receiving cells transduced by Hoxa9 virus alone also did not develop any leukemias, suggesting Hoxa9 by itself is not sufficient to transform GMPs." (PMID 29228732, 2017). "Interestingly, the expression of either HOXA9, a canonical downstream target for MLL-rearranged leukemia or ZNF521 have been shown to be restricted in CD34+ progenitor cells." (PMID 28412727, 2017). "In contrast, leukemia-initiating cells lacking mitochondrial Fh1 efficiently propagated Meis1/Hoxa9-driven leukemia." (PMID 28202494, 2017).
leukemia (continued). "Indeed, MYB is, in turn, a target of oncogenes such as HOXA9 and MLL fusions, and contributes to a leukemia stem cell maintenance signature conferring a self-renewal capability to myeloid progenitors." (PMID 28881700, 2017). "Highly potent and selective antagonists of such interactions have been shown to effectively disrupt the MLL1 complex with WDR5, and Menin and decrease the expression of HoxA9 and Meis‐1, inhibiting proliferation and inducing hematopoietic differentiation in MLL1 leukemia cells." (PMID 28160335, 2017). "Indeed, throughout the years, other molecules and pathways, besides the HOXA9/MEIS pathway, have been postulated to play roles in the survival of MLL-r leukemia cells such as CMYC, BCL2 and the NFκB pathway." (PMID 27317766, 2016). "Activation of an immune response may also reflect inherent inhibition of these pathways in MLLr and HOXA9-Meis-induced malignant cells, as recently reported for MN1, and highlight a potential therapeutic role for salinomycin in these specific leukemias." (PMID 27612428, 2016). "Next, we examined whether LSD1 inhibition can block the expression of HoxA9 and Meis1, whose overexpression has been observed in MLL-rearranged leukemia." (PMID 26970896, 2016). "In addition, in a mouse leukemia model generated by transplant of Bcr/Abl- and NUP98/HOXA9-transduced hematopoietic progenitor cells into sub-lethally irradiated recipients, CTLs recognizing antigens expressed in leukemia cells were exhausted." (PMID 26658107, 2015). "Meis1 cooperates with HoxA9 in leukemogenesis, as its overexpression accelerates the emergence of HoxA9-induced acute myeloid leukemia, whereas Prep1 overexpression does not accelerate HoxA9-induced leukemia but rather delays its onset." (PMID 26285139, 2015). "Next, we tested whether SYC-522 inhibited the expression of MLL-fusion target genes HOXA9 and MEIS1, both of which have been found to be overexpressed in MLL-rearranged leukemia and downregulated by treatment with a DOT1L inhibitor." (PMID 24858818, 2014). "Furthermore, deletion of Bcl-2 delayed the onset and reduced the severity of HoxA9/Meis1 and MLL-AF9 leukemias." (PMID 24177192, 2013). "Interestingly, the HOXA cluster genes, and especially HOXA4, HOXA5, HOXA9 and HOXA10, are also over-expressed in the MLL-rearranged leukemia cells." (PMID 24145746, 2013). "Analysis of the selected Hox A cluster and Hox cofactor genes revealed a high degree of co-expression between these in leukemia samples, where correlation coefficient between HOXA5, HOXA7, HOXA9 and MEIS1 ranged between 0.83 and 0.92 (Spearman rank correlation, p<0.0001 in all cases)." (PMID 17712416, 2007). "Taken together, our studies suggest a coordinated role for Cdx4 and the menin-MLL complex in modulating Hoxa9 expression during MLL-associated myeloid transformations, while Cdx4 is no longer required in full-blown leukemia cells such as AR1 cells." (PMID 17183676, 2006). "Expression of Hox genes (e.g. Hoxa9) is upregulated in human leukaemias carrying MLL rearrangements, and it has been shown recently that transformation by MLL fusion proteins requires Hoxa7 and Hoxa9, indicating that these are pivotal for MLL-associated leukaemogenesis." (PMID 14970850, 2004). "However, despite the functional significance of HOXA9 in leukemia, its functional regulators have not been systematically characterized at a genome-wide scale." (PMID 38216972, 2024). "Because overexpression of HOXA9 rescued the defects of leukemia growth after RBM5 loss, we speculate that the noncanonical transcriptional regulation of HOXA9 by RBM5 is one of the primary mechanisms in AML." (PMID 38216972, 2024). "Consequently, HOXA9 and MEIS1 are highly transcribed in MLL fusion-mediated leukemia." (PMID 34310280, 2021).
leukemia (continued). "Therefore, inhibition of DOT1L by SYC-522 treatment shows that reducing DOT1L methyltransferase activity and its downstream targets MEIS1 and HOXA9, can promote differentiation and might represent a valuable approach for treating MLL-rearranged leukemia." (PMID 34698191, 2021). "Moreover, we found that the enhanced RNA binding activity of MSI2 leads to differential regulation, e.g., at Hoxa9, Ikzf2, and Myb targets, in LSCs versus LSKs, which provides a possible explanation for the differential requirement of MSI2 in leukemia compared with normal hematopoiesis." (PMID 32332729, 2020). "Interestingly, HOXA9T, a homeodomain-less isoform of HOXA9, which is structurally similar to HOXB9v, has been demonstrated to act as an oncogene in leukemia without directly binding to DNA." (PMID 32104178, 2020). "Ash1l, Ctnnb1, Hoxa7, and Hoxa9 were also upregulated in the single mutant Mir-142−/− GMPs compared to WT, but the key co-factors Meis1 and Pbx3 were not, potentially explaining why these mice failed to develop leukemia." (PMID 33173219, 2020). "However, Meis1 alone does not induce leukemia, Meis1 as an accelerator of Hoxa9-induced leukemia but not stricto sensu as an oncogene." (PMID 31213012, 2019). "One of such peptidomimetic, MM-102, effectively decreases the expression of HOXA9 and Meis-1, two critical MLL/WDR5 target genes in MLL fusion protein-driven leukemogenesis, and specifically induces growth inhibition and apoptosis in leukemia cells harboring MLL fusion proteins." (PMID 30488017, 2018). "In addition, these leukemia cells did not express detectable levels of Hoxa9 or Hoxa10 protein, suggesting that their transformation is independent of Hoxa9 or Hoxa10 activation." (PMID 29228732, 2017). "Aberrant HOXA gene expression - in particular HOXA9 - leads to an enhanced colony forming capacity but the expression of MLL-AF9 in a Hoxa9−/− genetic background could not prevent leukemia development." (PMID 27175594, 2016). "Similarly, a trend for higher mRNA levels in resistant MLL-r leukemia cell lines was noted for HOXA9, albeit not significant." (PMID 27317766, 2016). "Although HOXA9 is not an ideal direct candidate for therapeutic interventions, uncovering the novel regulators of HOXA9 might elucidate the HOXA9 regulation mechanism that could be exploited to identify novel therapeutic targets in HOXA9-driven leukemias." (PMID 38216972, 2024). "Notably, HOXA9, one of the most important genes downstream of the MLL fusion oncoprotein, is reported to rewire gene regulatory networks by mediating the establishment of leukemia-specific enhancers, and the MLL fusion oncoprotein itself has the ability for enhancer binding." (PMID 33143730, 2020). "The long existing dogma within MLL-r leukemia research that HOXA9 is consistently highly expressed in all MLL-r leukemias has been challenged by several recent studies indicating that HOXA9 per se might not be required for all MLL-rearranged pediatric and infant ALL leukemias." (PMID 27317766, 2016). "All the MYC/HOXA9- and HOXA9/MEIS1-induced leukemias were positive to a myeloid marker Mac1 but negative to lymphoid marker B220 or CD3e, indicating that both MYC/HOXA9- and HOXA9/MEIS1-combinations induced myeloid leukemia." (PMID 34310280, 2021). "Although HOXA9 maintained MYC expression to immortalize myeloid progenitors ex vivo, it did not induce leukemia in vivo." (PMID 34310280, 2021). "We reasoned that the lower expression levels of HOXA9 and HOXA10 probably were a reflection of slower progressing of leukemia rather than a HoxB13 shRNA non-specific knockdown effect on the HoxA family members." (PMID 33037410, 2020). "Thus, MLL fusion proteins might promote leukemogenesis not only by HOXA9 and MEIS1 upregulation, but also by keeping the ZNF521 overexpressed, which in turn contributes to a block of differentiation or to the maintenance of an undifferentiated state of leukemia cells." (PMID 28412727, 2017).
leukemia (continued). "The 75KDa form also is predominantly expressed in Hoxa9- and Hoxa10-immortalized myeloid progenitors and Hoxa9/Hoxa10+BCR/ABL leukemia cells (data not shown)." (PMID 29228732, 2017). "Indeed, several of the IRF8/MEF2D direct target genes, such as MYC, HOXA9, and ZEB2, are highly expressed and essential in non-KMT2Ar leukemias and normal hematopoietic progenitors that do not express high levels of IRF8/MEF2D." (PMID 35301220, 2022). "Notably, after treating MV4;11 cells with 100 nM inhibitor for 7 days we observed no discernable effect on the expression of HOXA9 and MEIS1, despite the emphasis on these genes as the critical mediators of DOT1L’s effects in MLL-r leukemia." (PMID 34263728, 2021). "However, their expression did not correlate with HOXA5, HOXA7, HOXA9 or MEIS1 and only weakly with PBX3 expression in human leukemia (Spearman, r = 0.37, p = 0.033 and r = 0.44, p = 0.078 respectively)." (PMID 17712416, 2007).
acute myeloid leukemia (98 papers, 2009 to 2026). Acute myeloid leukemia (AML) is a group of neoplasms arising from precursor cells committed to the myeloid cell-line differentiation. "The effects of HOXA9 overexpression are well documented in acute myeloid leukemia (AML), where said overexpression is linked to poor prognosis." (PMID 35743243, 2022). "HOXA9 is overexpressed in more than 50% of acute myeloid leukemia (AML) cases and is associated with poor prognoses." (PMID 34367969, 2021). "The HOXA9 gene is of particular interest from a hematopoietic perspective as its dysfunction has been implicated in acute myeloid leukemia." (PMID 30674274, 2019). "Various genetic alterations occur in AML that lead to overexpression of the MEIS/HOXA9 complex, which plays a synergistic causative role in acute myeloid leukemia (AML) development." (PMID 28270206, 2017). "Abundant expression of HOXA9 in clinical samples of acute myelogenous leukemia is associated with adverse clinical outcomes." (PMID 26098938, 2015). "Moreover, similar findings in other tumors including glioblastoma and acute myeloid leukemia confirmed associations of HOXA9 with worse survival." (PMID 39462379, 2024). "In addition to acute myeloid leukemia, HOXA9 is also closely associated with ovarian cancer and glioma." (PMID 35783150, 2022). "Overexpression of HOXA9 is associated with poor prognosis of acute myeloid leukemia (AML)." (PMID 33224314, 2020). "In acute myeloid leukemia (AML) increased levels of Pim-1 have been associated with aberrant expression of the mixed-line-age leukemia (MLL) gene as a consequent activation of tyrosine-kinase receptor FLT3 or the transcriptional regulator Hoxa9." (PMID 25491234, 2014). "On the contrary, SETDB1 inhibits the expression of genes associated with acute myeloid leukemia (AML), such as Dock1, Hoxa9, and Six1, to delay MLL-AF9-mediated disease progression by promoting the differentiation of leukemia cells." (PMID 38057834, 2023). "Overall, we find that RBM5 is a new regulator in HOXA9 regulation and controls acute myeloid leukemia development." (PMID 38216972, 2024). "In acute myeloid leukemia (AML), it has been reported that the degradation of RBM39 represses cassette exon inclusion and promotes intron retention within mRNAs encoding HOXA9 targets and in other RNA-binding proteins (RBPs) preferentially required for AML survival." (PMID 38789724, 2024). "Different from the most common abnormal upregulation in acute myeloid leukemia, the HOXA9 gene is highly methylated and its downstream mRNA expression is significantly decreased in HCC, presenting the role of tumor suppressor genes." (PMID 37520979, 2023). "Although HOXA9 and MEIS1 play synergistic and pathogenic roles in acute myeloid leukemia (AML), both molecules are considered difficult to drug due to the lack of deep pockets for binding SMIs." (PMID 37496997, 2023). "HOXA9 overexpression is commonly observed in over 70% of human acute myeloid leukemia (AML) cases and ~10% of acute lymphoblastic leukemia (ALL) cases." (PMID 33001025, 2020). "HOXA9 is reported to play distinct roles in oncogenesis in acute myeloid leukemia, glioblastoma, and ovarian cancer and tumor suppression in breast, cervical, and hepatocellular cancer." (PMID 33238593, 2020). "Our analysis highlighted Meis1 and Hoxa9 as two factors with established roles of blocking myeloid differentiation, most notably in the context of acute myeloid leukaemia cells." (PMID 33103827, 2020). "Upregulation of HOXA9 has also been shown to sustain the self-renewal of HSC in acute myeloid leukemia (AML) and the NUP98-HOXA9 fusion protein induces long-term proliferation and impaired differentiation of leukemic CSC." (PMID 30974862, 2019). "HoxA9 is expressed in myeloid progenitors, with its level diminishing during myeloid maturation, and HOXA9 is over-expressed in a majority of acute myeloid leukemia cases, including those expressing NUP98-HOXD13." (PMID 31120998, 2019).